MUC1 (mucin 1, cell surface associated)
Diseases named in the same sentence as MUC1 in open-access papers (continued):
Sharing a sentence is not in itself a finding about the gene and the disease.
breast carcinoma (continued). "Paclitaxel was loaded in aptamer-conjugated NPs of PLGA and validated in a MUC1-overexpressing breast cancer cells." (PMID 35205658, 2022). "Currently, some anti-MUC1 monoclonal antibodies are widely used as a clinical tool to detect and monitor breast cancer." (PMID 35887202, 2022). "Firstly, they demonstrated that MUC1 was highly expressed on the exosome surface of MCF-7 breast cancer cells, which was significantly higher than in other cells." (PMID 36235208, 2022). "MUC1 plays a role in the regulation of chemoresistance in several cancer tissues, such as thyroid and breast cancers." (PMID 35054482, 2022). "Another CAR-T MUC1 currently in clinical evaluation is huMNC2-CAR44, targeting MUC1*, the extra cellular domain of the cleaved form of MUC1, present on a large percentage of solid tumors, including breast cancer (NCT04020575)." (PMID 35158915, 2022). "Dually aptamer-modified nano-systems against CD44 on CSCs and MUC1 on breast cancer cells displayed higher cellular uptake and efficacy against metastasis of breast cancer stem cells in athymic nude mice." (PMID 36559202, 2022). "MUC1 is a large transmembrane glycoprotein which is frequently overexpressed and aberrantly glycosylated in breast cancer." (PMID 35280770, 2022). "MUC1 is a highly glycosylated transmembrane protein, overexpressed in breast cancer, contributing to tumorigenesis and worse prognosis." (PMID 35970845, 2022). "Other studies involving MUC1 glycopeptide vaccines induced a monoclonal IgG specific to mammary tumors." (PMID 36291752, 2022). "This was supported by Western blot results showing decreased levels of large and small isoforms of MUC1 after expression of hsa-miR-145-5p in breast cancer cell lines." (PMID 34149728, 2021). "Mucin-1 (MUC1) is considered as a large membrane-bound glycoprotein which is aberrantly overexpressed in most human breast cancers and other malignancies such as pancreatic cancer, lung carcinoma, multiple myeloma, ovarian cancer, etc.." (PMID 34814824, 2021). "Here, we describe the generation of VLPs co-delivering two tumour antigens (MUC1 and survivin) and evaluate their efficacy as an immunotherapy in a murine breast cancer model." (PMID 34066318, 2021). "In vivo studies have also illustrated a significant increase in the IGF-1R phosphorylation compared to the control cells in MUC1-expressing murine breast cancer cells." (PMID 33836774, 2021). "In SCID mice model bearing human breast cancer cell line xenografts, MUC1-FA-[18F] SFB hybrid peptide demonstrated excellent tumor uptake and favorable pharmacokinetics over MUC1-[18F] SFB peptide conjugate." (PMID 33738611, 2021). "Interleukin-6 (IL-6) and IFN-γ activate STAT3 and STAT1 proteins, which bind to the MUC1 promoter region to enhance gene transcription in breast cancer cells." (PMID 34681277, 2021). "Previously, using a pull-down approach, the mucin-like proteins, CD43 and Muc-1, were identified as Siglec-1 counter-receptors on a T cell line and breast cancer cells, respectively." (PMID 35224210, 2021). "From an immunotherapeutic setting, a 15‐year follow‐up on clinical trials employing oxidized mannan–MUC1 revealed that treatment with the oxidized mannan–MUC1 significantly reduced the recurrence rate in stage II breast cancer patients." (PMID 33752265, 2021). "As a result, we demonstrated for the first time a potential role of MUC1/Y in cancer growth and proliferation in a mouse model of breast cancer and its potential as a target for anticancer therapeutics." (PMID 34452200, 2021). "In both cases, the breast cancer cells-derived exosomes depicted a much higher MUC1 fluorescence, indicating the potential use of this method for further diagnosis of breast cancer." (PMID 34073560, 2021).
breast carcinoma (continued). "Bruno used a biotin-conjugated DNA aptamer against MUC1 and a streptavidin-C1q fusion protein to trigger the classical complement pathway, and achieved a moderate killing effect on breast cancer cells." (PMID 35052426, 2021). "Directly competitive electrochemical immunosensors based on gelatin modifications of dopamine (DA)/MUC1-functionalized electroactive carbon nanotubes have also been designed to be used as signal generation probes for the early diagnosis of breast cancer." (PMID 34207342, 2021). "Recently, the synthesis and in vitro and in vivo characterization of new 99mTc-labeled-MUC1-derived peptide was reported suggesting the potential of this radiotracer for the targeted imaging of MUC1-positive breast cancer." (PMID 33738611, 2021). "Breast cancer patients with higher expression of MUC1 and MUC14 but with lower expression of MUC15 and MUC18 had better OS." (PMID 34828282, 2021). "CA15-3 is a soluble form of mucin 1 (MUC1), trans-membrane glycoprotein first recognised as a prognostic biomarker in breast cancer." (PMID 34957244, 2021). "For example, typical cancer markers for breast cancer are human mucin-1 (MUC1), a high molecular weight glycosylated membrane protein produced by epithelial tissues, and carcinoembryonic antigen (CEA)—the membrane glycoprotein involved in cell adhesion." (PMID 34073054, 2021). "In vitro binding studies on MCF7 breast cancer cell line showed superior affinity of MUC1-FA-[18F] SFB hybrid peptide over only MUC1-[18F] SFB peptide conjugate." (PMID 33738611, 2021). "It was found that dual-targeted T-cells co-expressing a HER2-and MUC-1-specific CAR effectively kill breast cancer cells that normally express both targets." (PMID 33442419, 2021). "MUC1 expression in breast cancer tissues was higher than that in normal breast tissues while MUC15, MUC14 and MUC18 were downregulated in cancer samples compared with normal controls." (PMID 34828282, 2021). "Over 90% of breast cancers overexpress MUC1, making it an ideal target for indiscriminate testing, as most patients with cancer will have the biomarker." (PMID 34439139, 2021). "The stable downregulation of MUC1 has been shown to increase the intracellular ROS levels and sensitize breast cancer cells to ROS-induced necrosis." (PMID 34681277, 2021). "Using a pancreatic ductal adenocarcinoma (PDA) and a breast cancer cell line (both devoid of MUC1), we report that there is increased expansion of MDSCs in the MUC1KO mice, and that the MDSCs are highly suppressive as compared to that of MDSCs in WT mice." (PMID 34070449, 2021). "In accordance with OS analysis, breast cancer patients with increased expression of MUC1 and MUC14 but decreased expression of MUC15 and MUC18 possessed favorable RFS." (PMID 34828282, 2021). "Peptide-based vaccines focus mainly on eliciting a cellular antigen-specific T-cell response against antigens highly expressed on tumor cells such as HER2 and MUC1 in breast cancer 70-72." (PMID 34729098, 2021). "Identical with the results from HPA database, MUC1 expression was significantly upregulated while MUC18 (MCAM) expression was obviously downregulated in breast cancer samples." (PMID 34828282, 2021). "Mucin 1 (MUC-1)-positive plasma cells were identified as a potential marker in the micrometastatic lymph nodes of breast cancer patients with high efficiency." (PMID 33441653, 2021). "GO conjugated to anti-MUC1 IgG through a thiol-ene coupling reaction successfully targeted breast cancer and exhibited higher toxicity." (PMID 34266419, 2021). "First, C57mg.MUC1 breast cancer cells were confirmed to express MUC1 in culture (left), as well as PD-L1 following interferon-γ (IFN-γ) stimulation (right) by flow cytometry." (PMID 34066318, 2021). "The experience of our research group proved that the combination of anti-MUC1 monoclonal antibody with cisplatin or etoposide led to a better anticancer effect in breast cancer cells than monotherapy." (PMID 34437575, 2021).
breast carcinoma (continued). "The prominent role of MUC1 in E. coli inv invasion was unexpected, as E. coli inv has not been reported to interact with MUC1 directly and MUC1 overexpression in breast cancer cells prevents ITGB1-mediated cell adhesion to extracellular matrix components." (PMID 33824202, 2021). "The cytoplasmic domain of MUC1 was found in breast cancer cell lines to be phosphorylated by ErbB1 at the YEKV motif, resulting in c-Src and β-catenin recruitment and downstream signaling." (PMID 34681277, 2021). "MUC1 is related to tumorigenicity and cell transformation, and approximately 90% of human breast cancers overexpress MUC1 (> tenfold)." (PMID 34266419, 2021). "The The Cancer Genome Atlas Breast Invasive Carcinoma (TCGA-BRCA) and Molecular Taxonomy of Breast Cancer International Consortium (METABRIC) datasets were analyzed for effects of MUC1 on GSEA, cell-type enrichment, and tumor immune dysfunction and exclusion." (PMID 33495298, 2021). "The results demonstrated that the 5E5-based CAR T cells significantly targeted multiple types of cancer cells expressing the Tn-MUC1, including breast cancer cells, leukemia cells, and pancreatic cancer cells." (PMID 34814824, 2021). "In breast cancer, MUC1 was shown to provide predictive information for therapy response and also for survival." (PMID 34386419, 2021). "MUC1 is a transmembrane glycoprotein that is considered as a potential biomarker for breast cancer diagnosis, since MUC1 is highly expressed in patients suffering from cancer disease." (PMID 33494499, 2021). "As an exception, in several studies of breast cancer, MUC1 positivity was found to correlate with adverse metastases stages, nodal status and histological grading as well as hormone insensitivity." (PMID 34386419, 2021). "Overexpression of C1GalT in breast cancer cells increased the MUC1 molecular size, an indication of increased MUC1 O-glycosylation." (PMID 34944925, 2021). "For this analysis, we assumed a good correlation of the immunohistochemical staining with the MUC1 expression on the transcriptional level which as it was shown for other solid cancer types e.g. breast cancer." (PMID 34386419, 2021). "Being highly overexpressed in breast cancer, human MUC1 is one of the most common tumour biomarkers for this disease diagnosis (the cancer cut-off level of MUC1 is 3.96 × 10−12 M)." (PMID 33499136, 2021). "On the other hand, due to the silencing of metastasis gene mucin 1 (MUC1), it is demonstrated that miR-145 can inhibit the invasion ability of metastatic breast cancer cell lines." (PMID 34307654, 2021). "In solid tumors, several tandem CARs have been tested in preclinical models including HER2 and IL13Ra2 in glioblastoma and HER2 and MUC1 in breast cancer." (PMID 33824268, 2021). "MUC-1 is highly expressed on the surface of breast cancer, ovarian and lung cancer and in this study, the efficacy of the carrier was determined against MCF-7 human breast cancer cell." (PMID 33498885, 2021). "The anti-tumor efficacy of MUC1-targeting CAR T cells was studied against breast cancer by comparing the single chain variable fragment (scFv), spacer length, and generations of CAR11." (PMID 33737613, 2021). "The proportion of MUC1 positives (59.0%) observed in the current study is however lower, compared to most Western studies, by stressing differences between breast cancer in African and Caucasians." (PMID 32377198, 2020). "Transcriptome analysis of the PyMT tumors from p11-KO mice showed marked reduction in genes such as Areg, Muc1, and S100a8 involved in breast cancer development, progression, and inflammation." (PMID 33297495, 2020).
breast carcinoma (continued). "Our results showed that these MUC1-C specific antibodies will be important tools for the understanding of MUC1 oncogenesis and are also highly effective therapeutic candidates against human breast cancers, especially TNBC cells." (PMID 32380650, 2020). "Alteration in expression of miR-497 (overexpression) and MUC1 (up- and down-regulation) was performed to examine their roles in breast cancer biology in vitro and in vivo." (PMID 33194611, 2020). "This study aims at addressing the expression profiles of MUC1 and other biomarkers in Ghanaian breast cancer and determines its predictive and prognostic characteristics, in relation to other clinicopathological features." (PMID 32377198, 2020). "Analysis of 53 whole primary breast cancers showed that a sialylated glycoform of MUC1, MUC1-ST (which carries the glycan, Neu5Acα2, 3Galβ1, 3GalNAc), was expressed by 83% of breast cancers." (PMID 33149188, 2020). "MUC1, a transmembrane mucin, has been demonstrated a potential prognostic and metastatic marker in breast cancer." (PMID 32377198, 2020). "The number of MUC-1+/CD44+ TMPs detected in plasma samples from 12 out of 15 breast cancer patients post-chemotherapy was 3–4-fold higher than those at baseline." (PMID 33050539, 2020). "hMUC1-1H7 is an anti-hMUC1 murine mAb developed against a recombinant MUC1 obtained from the breast cancer cell MCF7." (PMID 33167508, 2020). "This study sought to assess the predictive and prognostic significance of MUC1 in breast cancer presented by Ghanaian women in Kumasi." (PMID 32377198, 2020). "Because MUC1 is an indispensable mucin involved in breast cancer progression, this study provides direct evidence of the involvement of MUC1 glycosylation in a cancerous tumor conditions." (PMID 32075174, 2020). "It significantly reduced proliferation of breast cancer cells in which it is internalized and specifically localized in MUC1-expressing tumors in the xenograft mouse models." (PMID 33167508, 2020). "Alternatively, GGSK-1/30, which is a murine mAb specific for an alternative MUC1 glycoprotein epitope, was conjugated to 89Zr and evaluated for combined PET/MRI imaging of breast cancer-bearing human MUC1-expressing transgenic mice." (PMID 33371487, 2020). "The specific biomarkers also include more cancer-specific markers, such as HER2neu and MUC1 in breast cancer, androgen receptor (AR), early growth response gene (EGR) and PSA in prostate cancer." (PMID 32823926, 2020). "In conclusion, miR-497 down-regulated MUC1 expression and subsequently suppressed breast cancer progression, highlighting miR-497 to be a potential biomarker and therapeutic target for breast cancer therapy." (PMID 33194611, 2020). "This study is designed to assess the proportion of MUC1 positives and establish the predictive and prognostic significance of MUC1 in primary breast carcinoma presented by Ghanaian women in Kumasi." (PMID 32377198, 2020). "Antibodies recognizing the alpha, beta, and cytoplasmic tail of MUC1 were tested against the following representative breast cancer cell lines: MCF-7, BT-20, ZR-75-1, T47D, and MDA-MB-231." (PMID 32380650, 2020). "The Cox regression model for multivariate analysis of biomarkers expression indicated that PgR, Ki67, and MUC1 were independent predictors for BCSS in older women with ER-positive early breast cancer." (PMID 32726924, 2020). "To study the effect of miR-497 and MUC1 on the growth of breast cancer in vivo, we monitored the size and weight of tumor formation in nude mice under various treatments." (PMID 33194611, 2020). "Although MUC1 is overexpressed in the majority of breast cancer cases studied, there appears to be racial differences in the proportion of positives and associated prognosis." (PMID 32377198, 2020). "Similar peptide-based panning strategy has been used to isolate VHH against breast carcinoma proteins–Muc-1, CD44, and ScFv against human angiotensin-I and CXC chemokine receptor-2." (PMID 33425985, 2020).
breast carcinoma (continued). "MUC1 is highly expressed in various cancer cells especially in breast cancer cells, and there is evidence indicating that the application of antibodies to MUC1 in combination with dinuclear platinum (II) complex can improve breast cancer treatment response." (PMID 33194611, 2020). "Expression of MUC1 was increased in breast cancer cells (MDA-MB-453, MDA-MB-468, MCF-7, and MDA-MB-231) compared with that in normal epithelial cells (MCF-10A), where expression of MUC1 was highest in MCF-7." (PMID 33194611, 2020). "Overexpression of miR-497 inhibited breast cancer cell proliferation and invasion and promoted the apoptosis of breast cancer cells by down-regulating MUC1." (PMID 33194611, 2020). "We also evaluated the functionalities of these antibodies on the growth and invasion of MUC1-expressing breast cancer cell lines." (PMID 32380650, 2020). "The presence of circulating antibodies against MUC1 correlates with good prognosis in breast cancer patients." (PMID 32823603, 2020). "MUC1 was highly expressed in breast cancer tissues compared with the normal adjacent tissues (p < 0.05)." (PMID 33194611, 2020). "RT-qPCR results revealed significantly higher levels of MUC1 in breast cancer tissues than in normal adjacent tissues, and Pearson’s correlation coefficient suggested that MUC1 was negatively correlated with miR-497." (PMID 33194611, 2020). "Analysis of the breast cancer subtypes showed that triple negative breast cancers had the lowest expression of MUC1-ST and oestrogen receptor-positive breast cancers the highest." (PMID 33149188, 2020). "The present study explored how miR-497 regulates breast cancer progression in a MUC1-dependent manner." (PMID 33194611, 2020). "It has been reported that anti-KL-6/MUC1 mAb increased aggregation of MUC1 glycoproteins at one pole of the cell, called capping of MUC1 on the surface and facilitated E-cadherin-mediated cell-cell interaction in breast cancer cell lines YMB-S and ZR-75-1S." (PMID 33167508, 2020). "5E5 mAb showed high specificity to breast cancer cells and tissue and was used to develop MUC1 CAR-T cells." (PMID 33167508, 2020). "To address the role of MUC1 in canine mammary tumor cells, we artificially transduced the canine MUC1 gene into CIPp, a canine mammary tumor cell line." (PMID 33375426, 2020). "In contrast, mouse studies showed that MUC1 deficiency effectively mitigated tumor development and metastasis, and downregulation of MUC1 expression also promoted the pro-apoptotic activity of genotoxic agents on mammary tumor cells." (PMID 33375426, 2020). "By establishing a new canine mammary tumor cell line with a stable, high level of MUC1 expression, we successfully demonstrated that MUC1 overexpression significantly promoted the proliferation and migration of tumor cells." (PMID 33375426, 2020). "The MUC1 gene is overexpressed in human malignant breast tumors, allowing the use of gene product CA 15-3 as a tumor marker for breast cancer." (PMID 33282730, 2020). "Collectively, these results indicated that overexpression of MUC1 was beneficial for the proliferation and migration of canine mammary tumor cells." (PMID 33375426, 2020). "To address this question, we developed a new canine mammary tumor cell line, CIPp-MUC1, with an elevated expression level of MUC1." (PMID 33375426, 2020). "In the present study, we investigated the effect of overexpressed MUC1 in the development of canine mammary tumors by establishing a canine mammary tumor cell line with stable overexpression of MUC1." (PMID 33375426, 2020). "To investigate the role of overexpressed MUC1 in the development of canine mammary tumors, we established a xenograft mouse model." (PMID 33375426, 2020). "Clinical studies showed that the high expression of mucin 1 (MUC1) protein is significantly associated with the malignancy and poor prognosis of canine mammary tumor." (PMID 33375426, 2020).